SCN2B (sodium voltage-gated channel beta subunit 2)
Description:
Regulatory subunit of multiple voltage-gated sodium (Nav) channels directly mediating the depolarization of excitable membranes. Navs, also called VGSCs (voltage-gated sodium channels) or VDSCs (voltage-dependent sodium channels), operate by switching between closed and open conformations depending on the voltage difference across the membrane. In the open conformation they allow Na(+) ions to selectively pass through the pore, along their electrochemical gradient. The influx of Na+ ions provokes membrane depolarization, initiating the propagation of electrical signals throughout cells and tissues. The accessory beta subunits participate in localization and functional modulation of the Nav channels. Modulates the activity of SCN1A/Nav1.1, SCN2A/Nav1.2, SCN2A/Nav1.3, SCN5A/Nav1.5, SCN8A/Nav1.6, SCN9A/Nav1.7 and SCN10A/Nav1.8.
Synonyms: ATFB14
Tractability: Small molecule: a structure with a bound ligand is known; a high-quality ligand is known. Antibody: UniProt places it where antibodies can reach, with high confidence; its Gene Ontology location is reachable by antibodies, with high confidence; UniProt predicts a signal peptide or a membrane-spanning region. PROTAC: a small molecule that binds it is known.
Target class: Sodium channel auxiliary subunit beta family; Auxiliary transport protein
Safety:
Unwanted effects reported when the protein is acted on. In parentheses: how it was acted on, where the effect was seen, and who reports it.
agitation (inhibition, acute dosing; nervous system, respiratory, cardiovascular; source: Lynch et al. (2017))
cardiac arrhythmia (inhibition, acute dosing and activation, acute dosing; nervous system, respiratory, cardiovascular; source: Lynch et al. (2017))
coma (inhibition, acute dosing; nervous system, respiratory, cardiovascular; source: Lynch et al. (2017))
convulsions (activation, acute dosing; nervous system, respiratory, cardiovascular; source: Lynch et al. (2017))
decreased blood pressure (inhibition, acute dosing; nervous system, respiratory, cardiovascular; source: Lynch et al. (2017))
decreased cardiac conduction (inhibition, acute dosing; nervous system, respiratory, cardiovascular; source: Lynch et al. (2017))
decreased cardiac contractility (inhibition, acute dosing; nervous system, respiratory, cardiovascular; source: Lynch et al. (2017))
decreased gastrointestinal transit (inhibition, acute dosing; nervous system, respiratory, cardiovascular; source: Lynch et al. (2017))
decreased locomotor activity (activation, acute dosing; nervous system, respiratory, cardiovascular; source: Lynch et al. (2017))
decreased pain (inhibition, acute dosing; nervous system, respiratory, cardiovascular; source: Lynch et al. (2017))
decreased respiratory rate (inhibition, acute dosing; nervous system, respiratory, cardiovascular; source: Lynch et al. (2017))
decreased sweating (inhibition, acute dosing; nervous system, respiratory, cardiovascular; source: Lynch et al. (2017))
decreased urine excretion (inhibition, acute dosing; nervous system, respiratory, cardiovascular; source: Lynch et al. (2017))
decreased/increased convulsions (inhibition, acute dosing; nervous system, respiratory, cardiovascular; source: Lynch et al. (2017))
decreased/increased heart rate (inhibition, acute dosing; nervous system, respiratory, cardiovascular; source: Lynch et al. (2017))
dyspnea (activation, acute dosing; nervous system, respiratory, cardiovascular; source: Lynch et al. (2017))
increased heart rate (activation, acute dosing; nervous system, respiratory, cardiovascular; source: Lynch et al. (2017))
increased pupil diameter (inhibition, acute dosing; nervous system, respiratory, cardiovascular; source: Lynch et al. (2017))
increased QRS complex (inhibition, acute dosing; nervous system, respiratory, cardiovascular; source: Lynch et al. (2017))
Gene: Protein-coding gene on chromosome 11 (118,162,806 to 118,176,639, reverse strand). Ensembl gene ENSG00000149575.
Subcellular location: Cell membrane; Cell projection, axon
Pathways (Reactome):
Developmental Biology: Interaction between L1 and Ankyrins
Muscle contraction: Phase 0 - rapid depolarisation
Sensory Perception: Sensory perception of sweet, bitter, and umami (glutamate) taste
Gene Ontology:
Molecular function: protein binding; sodium channel regulator activity; voltage-gated potassium channel activity involved in ventricular cardiac muscle cell action potential repolarization; voltage-gated sodium channel activity; voltage-gated sodium channel activity involved in cardiac muscle cell action potential
Biological process: cardiac muscle cell action potential involved in contraction; cardiac muscle contraction; membrane depolarization during action potential; membrane depolarization during cardiac muscle cell action potential; positive regulation of sodium ion transport; regulation of atrial cardiac muscle cell membrane depolarization; regulation of heart rate by cardiac conduction; cardiac conduction; chemical synaptic transmission; regulation of membrane potential; membrane repolarization during ventricular cardiac muscle cell action potential; nervous system development; response to pyrethroid; sodium ion transmembrane transport
Cellular component: plasma membrane; voltage-gated sodium channel complex; cation channel complex; axon; axon initial segment; membrane; node of Ranvier; synapse; T-tubule
Genetic constraint (gnomAD): Loss-of-function variants: 14 observed, 19.03 expected, observed/expected ratio (o/e) 0.74, 90% interval 0.49 to 1.15. The upper end of that interval is the gene's LOEUF score, 1.15, which puts it in group 5 of 6, group 1 being the genes least tolerant of losing a copy. Missense variants: 262 observed, 300.08 expected, observed/expected ratio (o/e) 0.87, 90% interval 0.79 to 0.97. Synonymous variants: 115 observed, 120.11 expected, observed/expected ratio (o/e) 0.96, 90% interval 0.82 to 1.12.
Gene-disease validity (ClinGen):
ClinGen rates the evidence that SCN2B causes each of these diseases.
Brugada syndrome 1 (autosomal dominant): Disputed.
Homologues: Orthologues: chimpanzee SCN2B (99% identical), macaque SCN2B (99% identical), pig SCN2B (94% identical), dog SCN2B (94% identical), rat Scn2b (93% identical), mouse Scn2b (92% identical), rabbit SCN2B (92% identical), guinea pig SCN2B (88% identical), tropical clawed frog scn2b (59% identical), zebrafish scn2b (51% identical). Paralogues in human: MPZL2 (25% identical), SCN4B (24% identical), JAML (24% identical), MPZL1 (23% identical), MPZ (22% identical), MPZL3 (22% identical).
Diseases named in the same sentence as SCN2B in open-access papers:
SCN2B is named in the same sentence as 31 diseases in open-access papers, as found by Europe PMC text mining. Sharing a sentence is not in itself a finding about the gene and the disease. The quoted sentences say what the papers report.
atrial fibrillation (5 papers, 2011 to 2023). A disorder characterized by an electrocardiographic finding of a supraventricular arrhythmia characterized by the replacement of consistent P waves by rapid oscillations or fibrillatory waves that vary in size, shape and timing and are accompanied by an irregular ventricular response. "Namely, the down-regulation of NKX2-5 indicates a deviation from cardiac tissue, accompanied by electrical remodelings, i.e., the down-regulation of KCNH2 and SCN2B, resulting in the formation of atrial fibrillation." (PMID 37445678, 2023). "Some previous studies have established that genetic modification in sodium voltage-channel genes encoding for the cardiac β-subunits, such as SCN1B, SCN2B, SCN3B and SCN4B, can result in atrial fibrillation (AF)." (PMID 36362949, 2022). "SCN2B encodes the beta 2 subunit of the type II voltage‐gated sodium channel and defects in SCN2B are related to Brugada Syndrome, atrial fibrillation, and sudden infant death syndrome." (PMID 36305047, 2022). "SCN2B gene alterations lead to autosomal dominant Brugada syndrome, atrial fibrillation, and sudden infant death syndrome." (PMID 33829027, 2021).
Brugada syndrome (5 papers, 2018 to 2024). A genetically heterogeneous condition characterized by complete or incomplete right bundle branch block accompanied by ST elevation in leads V1-V3. "By identifying timepoints in development where SCN2B expression occurs, we will be better placed to understand how mutations within a sodium channel subunit can alter myocyte function, which ultimately leads to Brugada syndrome." (PMID 30337648, 2018). "Mutations in SCN2B have been characterised in human Brugada syndrome sufferers, with the likely consequence of these mutations being to disrupt the ability of β2-subunits to chaperone voltage-gated sodium channel α-subunits, particularly Nav 1.5, to the plasma membrane." (PMID 30337648, 2018). "Other genes, such as SCN1B, SCN2B, SCN3B, and GPD1L, contribute to reduced INa and Brugada syndrome, with various clinical phenotypes associated with these mutations." (PMID 39583597, 2024).
epilepsy (5 papers, 2016 to 2024). A brain disorder characterized by episodes of abnormally increased neuronal discharge resulting in transient episodes of sensory or motor neurological dysfunction, or psychic dysfunction. "Likewise, 12/28 genes have been implicated in epilepsy or have a close family member established to increase risk including SCN2B, CALM1, CALM2, and APP." (PMID 26824476, 2016). "This study investigated several genetic variants of SCN genes (SCN1A, SCN2A, SCN3A, SCN1B, SCN2B, SCN3B and SCN8A) and their association with epilepsy risk; these genes have been studied in this regard and conflicted results were reported." (PMID 35801810, 2022).
cardiac arrhythmia (2 papers, 2016 to 2020). Any disturbances of the normal rhythmic beating of the heart or MYOCARDIAL CONTRACTION. "The sequence variations of SCN2B have been associated with human cardiac arrhythmias and genetic deletion of Scn2b in mice leads to ventricular and atrial arrhythmias." (PMID 33160353, 2020).
glioma (2 papers, 2021). A benign or malignant brain and spinal cord tumor that arises from glial cells (astrocytes, oligodendrocytes, ependymal cells). "Importantly, previous studies reported that AIFM3, LDHD, LYNX1, SCN2B or TMEM56 were all negatively corelated with glioma, and GINS1, KIFC1, NUF2, NUSAP1 or TPX2 were both positively related to glioma progression." (PMID 33277782, 2021).
prostate carcinoma (2 papers, 2019 to 2020). A carcinoma that arises from epithelial cells of the prostate gland. "Two other genes that were found in this study to interact in association with GCNT1 are SCN2B and SCN4B, components of voltage-gated sodium channels, and both of these factors have been previously associated with the developing prostate cancer and promoting cancer metastasis." (PMID 32915819, 2020).
breast carcinoma (1 paper, 2024). "SCN2B is a novel adhesion molecule that promotes the migration of human breast cancer cells." (PMID 38482382, 2024).
cardiac conduction disease (1 paper, 2013). "Finally, CACNB2 is associated with the regulator of the voltage-gated calcium channels RIM1, and with the sodium channel SCN2B, through its interaction with CACNA1B, since it has been described that a mutation in CACNB2b, and a mutation in SCN5A underlie cardiac conduction disease.." (PMID 24339868, 2013).
cardiomyopathy (1 paper, 2021). A disease of the heart muscle or myocardium proper. "Father (III:4) and aunt (III:3) had the same variants in genes: ABCG8, BIN1, SCN2B, and SYNE1 (related to Emery-Dreifuss muscular dystrophy with cardiomyopathy, cardiac conduction defects, and cerebellar ataxia)." (PMID 33829027, 2021).
cervical cancer (1 paper, 2018). A primary or metastatic malignant neoplasm involving the cervix. "In cervical cancer tissues, SCN3B mRNA level is increased, whereas SCN1B, SCN2B and SCN4B mRNA levels are decreased." (PMID 29723302, 2018).
cognitive diseases (1 paper, 2020). "Furthermore, SCN2B and SCN4B were also identified in two studies for their potential effects in the neuronal development, brain functions and cognitive diseases." (PMID 32915819, 2020).
familial atrial fibrillation (1 paper, 2023). An autosomal dominant heart condition that causes disruptions in the heart's normal rhythm. "The SCN2B gene encodes for the β 2 subunit of type II voltage-gated sodium channel and is associated with familial atrial fibrillation." (PMID 37834023, 2023).
lung carcinoma (1 paper, 2018). "Each of the other SNPs, including KCNJ4 rs138396 and SCN2B rs7944321, appeared to have a slightly elevated risk of lung cancer in discovery and replication." (PMID 30104567, 2018).
cancer (4 papers, 2016 to 2025). A tumor composed of atypical neoplastic, often pleomorphic cells that invade other tissues. "While reduced expression of either SCN1B/β1 or SCN2B/β2 decreased cancer cell invasiveness through Matrigel-coated invasion chambers by 42.8±6.6% (n=8) and 51.7±0.3% (n=8) (mean±s.e.m." (PMID 27917859, 2016). "SCN2B appeared to be weakly expressed in A549 cancer and NL-20 non-cancer cells, whereas not expressed at all in H23, H460, and Calu-1 cancer cell lines." (PMID 33817575, 2021). "Expressions of SCN1B, SCN2B and SCN3B were lower in cancer compared with non-cancer tissues." (PMID 27917859, 2016).
tumor (1 paper, 2024). "Among the potential transcripts, high levels of SCN2B in tumor tissues predict poor survival in patients with BLCA (p = 0.0073, log-rank test), suggesting that m1A-regulated mRNAs may be used as biomarkers in BLCA survival prediction." (PMID 38482382, 2024).
SCN2B also shares sentences with these, for which no sentence is quoted: heart failure (3 papers); sudden infant death syndrome (2); Alzheimer disease (1); autism (1); cerebellar ataxia (1); cerebral malaria (1); channelopathies (1); cognitive deficits (1); Emery-Dreifuss muscular dystrophy (1); gynecological cancers (1); heart disease (1); Hypertension (1); long-QT syndrome (1); memory impairment (1); prostate (1); schizophrenia (1).